ENSG00000238804
Synonyms: LOC124904116
Gene: Small nucleolar RNA gene on chromosome 17 (48,956,650 to 48,956,753, reverse strand). Ensembl gene ENSG00000238804.
Gene Ontology:
Biological process: RNA processing
Cellular component: nucleolus
Homologues: Paralogues in human: SNORD13P1 (88% identical), SNORD13 (88% identical), SNORD13P3 (87% identical), SNORD13D (83% identical), SNORD13E (80% identical).